C1QTNF6 (C1q and TNF related 6)
Synonyms: CTRP6; ZACRP6; CTFP6
Tractability: Antibody: UniProt places it where antibodies can reach, with high confidence; UniProt predicts a signal peptide or a membrane-spanning region; its Gene Ontology location is reachable by antibodies, with medium confidence.
Gene: Protein-coding gene on chromosome 22 (37,180,166 to 37,199,385, reverse strand). Ensembl gene ENSG00000133466.
Subcellular location: Secreted
Subcellular location (Human Protein Atlas): Nucleoplasm; Predicted to be secreted
Gene Ontology:
Molecular function: protein binding; identical protein binding
Cellular component: extracellular region; protein-containing complex
Genetic constraint (gnomAD): Loss-of-function variants: 17 observed, 20.3 expected, observed/expected ratio (o/e) 0.84, 90% interval 0.57 to 1.26. The upper end of that interval is the gene's LOEUF score, 1.26, which puts it in group 5 of 6, group 1 being the genes least tolerant of losing a copy. Missense variants: 329 observed, 403.74 expected, observed/expected ratio (o/e) 0.81, 90% interval 0.74 to 0.89. Synonymous variants: 130 observed, 160.94 expected, observed/expected ratio (o/e) 0.81, 90% interval 0.7 to 0.93.
Homologues: Orthologues: chimpanzee C1QTNF6 (99% identical), macaque C1QTNF6 (91% identical), pig C1QTNF6 (69% identical), dog C1QTNF6 (68% identical), rat C1qtnf6 (64% identical), mouse C1qtnf6 (64% identical), zebrafish c1qtnf6a (47% identical), guinea pig C1qtnf6 (30% identical). Paralogues in human: C1QTNF1 (44% identical), C1QTNF8 (44% identical), C1QTNF3 (24% identical), C1QL2 (23% identical), C1QL3 (23% identical), C1QTNF2 (23% identical), C1QTNF9 (23% identical), C1QTNF5 (22% identical), C1QTNF9B (22% identical), COL10A1 (22% identical), OTOL1 (22% identical), C1QC (22% identical), and 11 more.
Diseases named in the same sentence as C1QTNF6 in open-access papers:
C1QTNF6 is named in the same sentence as 82 diseases in open-access papers, as found by Europe PMC text mining. Sharing a sentence is not in itself a finding about the gene and the disease. The quoted sentences say what the papers report.
lung adenocarcinoma (12 papers, 2020 to 2025). A carcinoma that arises from the lung and is characterized by the presence of malignant glandular epithelial cells. "In lung adenocarcinoma high expression of C1QTNF6 has also been associated with poor prognosis." (PMID 36809527, 2023). "The results showed that compared to BEAS-2B cells, KRT80, TRPA1, and C1QTNF6 were highly expressed in two lung adenocarcinoma cell lines (A549 and NCI-H1299)." (PMID 39247607, 2024). "C1q/tumor necrosis factor-related protein 6 (C1QTNF6) is a glycoprotein composed of 259 amino acids, which plays an important role in predicting the prognosis of many cancers, including lung adenocarcinoma, bladder cancer, and gastric cancer." (PMID 35942407, 2022). "This study aimed to explore the function of C1qtnf6 in lung adenocarcinoma (LUAD) progression." (PMID 40490027, 2025). "However, the biological process and potential mechanism of C1QTNF6 in lung adenocarcinoma (LUAD) are indefinite and remain to be elucidated." (PMID 35879698, 2022). "For the development of malignancies, upregulation of C1QTNF6 was observed for stage I lung adenocarcinoma in contrast to the adjacent noncancer tissues." (PMID 40270961, 2025).
lung carcinoma (11 papers, 2020 to 2025). "Consistent with our results, other PSMC signature-related genes, including LDHA, SEC61G, PLEK2, and C1QTNF6, have been shown to be risk genes in lung cancer in vitro, mediating the development, growth, and metastasis of lung cancer." (PMID 36699466, 2022). "Although emerging evidence has indicated C1QTNF6 modulated cellular apoptosis in lung cancer, the biological process and underlying mechanism of C1QTNF6 in LUAD still remain unknown." (PMID 35879698, 2022). "By analyzing the TCGA database, we identified C1qtnf6 as a potential candidate target for lung cancer." (PMID 40490027, 2025). "Further investigating C1qtnf6 in the context of LUAD would establish its potential as a therapeutic target in the clinical treatment of lung cancer; hence, compilation of further evidence is warranted." (PMID 40490027, 2025). "Following C1qtnf6 knockdown, increased apoptosis was observed in both H1975 and A549 lung cancer cells." (PMID 40490027, 2025). "Second, to comprehend the mechanism of C1qtnf6‐mediated immune infiltration in lung cancer more thoroughly, conducting both in vitro and in vivo studies is crucial." (PMID 40490027, 2025). "The expression and function of C1qtnf6 in lung cancer were examined by analyzing data from the TCGA database to determine the prognostic importance of this protein in LUAD." (PMID 40490027, 2025). "These investigations would advance the knowledge of the C1qtnf6 function in the immune infiltration mechanism in lung cancer and offer insights into the specifics." (PMID 40490027, 2025). "Through an analysis of lung cancer cases in the TCGA database, we discovered that C1qtnf6 exhibits high expression in the tumor tissues of lung cancer patients, which correlates with poorer OS rates." (PMID 40490027, 2025). "The findings of this study would provide valuable evidence for considering C1qtnf6 as a target in the clinical management of lung cancer." (PMID 40490027, 2025). "C1QTNF6 had been found to be upregulated in stage I lung cancer tissue and regulated by MIR-29 A-3P to promote proliferation." (PMID 38711158, 2024). "Additionally, MTS and flow cytometric analyses revealed that lung cancer cell growth and apoptosis are both enhanced by C1qtnf6." (PMID 40490027, 2025). "However, the precise function of C1qtnf6 in lung cancer remains unclear." (PMID 40490027, 2025). "In terms of predictive and prognostic value, the ROC values for C1qtnf6 in LUAD demonstrated high sensitivity and specificity, comparable to or exceeding those of several established lung cancer biomarkers." (PMID 40490027, 2025). "Four genes (C1QTNF6, DLGAP5, HMMR, and PLEK2) were identified as key genes in LUAD progression, which were upregulated in the cancerous tissue compared with in the normal tissue (P < 0.001), and correlated with an unwanted prognosis in lung cancer (P < 0.05)." (PMID 37910672, 2023).
gastric cancer (10 papers, 2020 to 2025). A primary or metastatic malignant neoplasm involving the stomach. "For instant, C1QTNF6 was found to be upregulated and to be associated with initiation and progression in multiple malignant tumors including clear cell renal cell carcinoma, gastric cancer, HCC and NSCLC." (PMID 35879698, 2022). "C1QTNF6 is involved in promoting proliferation and migration as well as in reducing the apoptosis of gastric carcinoma cells and NSCLC." (PMID 34906149, 2021). "Consistent with our observation, the expression of C1QTNF6 in human gastric carcinoma tissues has been shown to be higher than that in normal gastric tissue, and C1QTNF6 silencing in gastric carcinoma cells decreased the growth and resulted in G2‐M cell cycle arrest." (PMID 34906149, 2021). "Interestingly, C1QTNF6 knockout can significantly decrease the proliferation and metastatic ability of gastric cancer cells." (PMID 33123583, 2020). "It has also been reported that C1QTNF6 is overexpressed in gastric cancer." (PMID 33123583, 2020).
hepatocellular carcinoma (9 papers, 2015 to 2025). A malignant tumor that arises from hepatocytes. "Genes such as LAMA4, LAMA5, and C1QTNF6 were involved in angiogenesis in many cancer types such as renal cell carcinoma, colorectal cancer, and hepatocellular carcinoma, but these genes may be linked with angiogenesis in GBM." (PMID 31137733, 2019). "In particular, C1QTNF6 has been shown to be overexpressed in hepatocellular carcinoma tissues and many HCC cell lines, and C1QTNF6 has been shown to promote neovascularization in transplanted HCC cells." (PMID 34906149, 2021). "It has been reported that C1QTNF6 was upregulated in hepatocellular carcinoma (HCC) and inhibition of C1QTNF6 could prevent survival, migration and promote apoptosis in HCC cells by inactivation of the AKT signaling pathway." (PMID 35879698, 2022).
Arthritis (8 papers, 2015 to 2026). Inflammation of a joint. "This gene is implicated in arthritis, and intra-articular injection of the recombinant C1qTNF6 protein was shown as an effective strategy in improving arthritis and inflammation in C1qtnf6−/− mice." (PMID 32511341, 2020). "C1qtnf6−/− mice are highly susceptible to induced arthritis due to enhanced complement activation, whereas C1qtnf6-transgenic mice are refractory." (PMID 26404464, 2015). "While the partial fetal loss in C1qtnf6-deficient mice was previously noticed by an arthritis-focused study, the detailed characteristics and underlying mechanism of this phenotype remains unclear." (PMID 41568145, 2026). "C1QTNF6 (-/-) mice were extremely prone to induced arthritis because of augmented complement activation." (PMID 40270961, 2025). "Intra-articular injection of arthritis-induced mice with recombinant human C1QTNF6 cured the disease, which suggested that this protein is a novel target for the treatment of inflammatory diseases." (PMID 40270961, 2025). "We examined the susceptibility of C1qtnf6 Tg mice to CIA, using a higher concentration of M. tuberculosis (2.5 mg ml−1) in CFA to induce severe arthritis." (PMID 26404464, 2015). "We also analysed susceptibility of C1qtnf6−/− mice to CAIA6, in which antibodies against IIC were directly injected to induce arthritis." (PMID 26404464, 2015). "Because C1qtnf6 is highly expressed in mouse RA models, we generated C1qtnf6−/− mice to elucidate the pathological roles of CTRP6 in the development of arthritis." (PMID 26404464, 2015). "By contrast, in C1qtnf6−/− mice, the onset of arthritis was earlier, and the severity score was higher than in WT mice, although the incidence of arthritis was similar between the two strains." (PMID 26404464, 2015). "Interestingly, one study found that CTRP6 can be used to treat induced arthritis and noticed that C1qtnf6−/− embryos are semi-lethal in mice." (PMID 41568145, 2026).
rheumatoid arthritis (7 papers, 2015 to 2025). A chronic, systemic autoimmune disorder characterized by inflammation in the synovial membranes and articular surfaces. "C1QTNF6 is a known susceptibility locus for Type 1 Diabetes and is implicated in Rheumatoid Arthritis, and a suggestive association with SLE has recently been described in a transancestral Immunochip analysis." (PMID 29177435, 2018). "A study by the Institute of Medical Science from the University of Tokyo showed a higher expression of C1QTNF6 in mouse models with rheumatoid arthritis." (PMID 40270961, 2025). "The immune-modulatory role of C1QTNF6 has been recognized in other autoimmune diseases, such as rheumatoid arthritis, where its expression and function in immune cells contribute to either promoting or suppressing autoimmunity, depending on the genetic context." (PMID 40270961, 2025). "Here we show that C1q/TNF-related protein 6 (CTRP6; gene symbol C1qtnf6) expression is elevated in mouse rheumatoid arthritis (RA) models." (PMID 26404464, 2015). "In C1QTNF6−/− mice, C1QTNF6 was demonstrated to serve as a novel regulator of the complement alternative pathway with potential to treat rheumatoid arthritis in clinical studies." (PMID 34906149, 2021).
bladder cancer (6 papers, 2020 to 2025). "High C1QTNF6 expression may serve as a predictor of poor prognosis in bladder cancer patients, and the underlying mechanism is possibly associated with changes on cancer cell migration and invasion ability." (PMID 33123583, 2020). "This study is aimed at providing some promising molecular biomarkers for bladder cancer (BC) by investigating the correlation between C1QTNF6 expression and clinical characteristics as well as prognosis in patients with bladder cancer." (PMID 33123583, 2020). "Respective results indicated that, in patients with high C1QTNF6 levels, genes that were enriched in particular networks, including bladder cancer, cytokine-cytokine receptor interaction, ECM receptor interaction, ERBB signaling pathway, and melanoma, varied significantly." (PMID 33123583, 2020). "Similarly, C1QTNF6 mRNA and protein expressions were found to be remarkably high in bladder cancer (BC) and higher C1QTNF6 expression may predict as an adverse prognostic marker for BC patients." (PMID 35879698, 2022). "The underlying mechanism related to this differential expression could be explained by cell migration and invasion assays, where bladder cancer cells 5637 and T24 had a significant reduction on migration and invasion ability upon knockdown of C1QTNF6 expression." (PMID 33123583, 2020). "However, the biological functions of C1QTNF6 in bladder cancer (BC) have been very limited." (PMID 33123583, 2020).
breast cancer (6 papers, 2017 to 2025). A primary or metastatic malignant neoplasm involving the breast. "C1QTNF6 down-regulation has previously been studied to possibly increase breast cancer invasion in vitro but also being overexpressed in multiple cancer types contributing to cancer proliferation, migration and possibly tumor angiogenesis." (PMID 36809527, 2023). "This is in line with a previous study on breast cancer cells showing that C1QTNF6, SPARC, and COL4A2 were targeted by miR-29b." (PMID 29176935, 2017). "If hsa-miR-96 directly interacts with C1QTNF6, FN1, and TFGB1 in breast cancer, the expression level of mRNAs should be down-regulated because the overexpressed hsa-miR-96 will suppress the mRNA’s expression." (PMID 28793339, 2017). "Most importantly, there are several genes that can distinguish the four breast cancer subtype as specific therapeutic targets for each subtype, including EFCAB2 for luminal A, ATG16L2 for luminal B, C1QTNF6 and NDUFS6 for HER2+, as well as CHERP, TIAM1, and GABRP for TNBC." (PMID 28245581, 2017).
oral squamous cell carcinoma (6 papers, 2021 to 2025). "A similar role of C1QTNF6 was also recognized in oral squamous cell carcinoma, as C1QTNF6 knockdown led to cell cycle arrest at phase G2/M and enhancement of cancer cell apoptosis." (PMID 40270961, 2025). "However, the role of C1QTNF6 in oral squamous cell carcinoma (OSCC) and its potential molecular remains unclear." (PMID 34906149, 2021).
autoimmune disease (5 papers, 2015 to 2026). A disorder resulting from loss of function or tissue destruction of an organ or multiple organs, arising from humoral or cellular immune responses of the individual to their own tissue constituents. "Despite that the C3 expression in MFI remained constant (or even increased) after C1qtnf6-KO, we found its protein abundance is decreased—a sign for complement activation and assumption according to previous studies on autoimmune diseases." (PMID 41568145, 2026).
clear cell renal cell carcinoma (4 papers, 2021 to 2025). "Recently, C1QTNF6 was shown to be overexpressed in clear cell renal cell carcinoma, with correlation between elevated C1QTNF6 expression and clinical progression." (PMID 34906149, 2021). "Furthermore, C1QTNF6-related signaling pathways activated in clear cell renal cell carcinoma have been shown to be mainly enriched in DNA replication, Cell Cycle, EMT, and angiogenesis signaling pathways." (PMID 34906149, 2021).
ischemic stroke (4 papers, 2022 to 2024). A stroke disorder caused by obstruction of blood flow to the brain, due to thrombotic (local blood clot formation) or embolic (due to a blood clot or other material traveling from another site) event. "In this study, mRNA expression of C1QTNF6 in neutrophils following ischemic stroke significantly increased compared to that of healthy controls (P < 0.05)." (PMID 36052307, 2022). "In summary, this is the first study to demonstrate H19 and C1QTNF6 upregulation and miR‐29b downregulation in leukocytes of patients with ischemic stroke and MCAO rats." (PMID 35322553, 2022). "We found an alteration in the expression of C1q and tumor necrosis factor 6 (C1QTNF6) after ischemic stroke." (PMID 35322553, 2022). "Leukocytic miR-29b attenuates inflammatory response by augmenting BBB integrity through C1QTNF6, suggesting a novel miR-29b-based therapeutic therapy for ischemic stroke." (PMID 36052307, 2022). "This study aimed to elucidate the inflammatory mechanism of long non‐coding RNA (lncRNA) H19‐mediated regulation of C1q and tumor necrosis factor 6 (C1QTNF6) by sponging miR‐29b in leukocytes during ischemic stroke." (PMID 35322553, 2022). "This study showed abnormally high expression of C1QTNF6 in leukocytes of patients with ischemic stroke and in MCAO rats." (PMID 36052307, 2022). "This study aimed to elucidate the inflammatory mechanism of lncRNA H19‐mediated regulation of C1QTNF6 by sponging miR‐29b in leukocytes during ischemic stroke." (PMID 35322553, 2022). "Therefore, we hypothesized that C1QTNF6 in leukocytes might be regulated by H19 and miR‐29b that are probably involved in the pathogenesis of ischemic stroke." (PMID 35322553, 2022).
type 1 diabetes (4 papers, 2018 to 2025). "Genome-wide association study identified C1QTNF6 as a candidate gene for type 1 diabetes (T1D) in Caucasians." (PMID 40270961, 2025).
liver cancer (3 papers, 2020 to 2023). An epithelial or non-epithelial malignant neoplasm that arises from the liver. "Moreover, the recombinant protein C1QTNF6 appears to effectively increase the expression of Akt and promote liver cancer angiogenesis." (PMID 33123583, 2020). "Additional studies have indicated that C1QTNF6 depletion may negatively impact the invasion and migration of liver cancer cells by inactivating the AKT pathway." (PMID 33123583, 2020). "Among 30 liver cancer samples, 21 has been positive for C1QTNF6, while normal liver tissues are typically negative." (PMID 33123583, 2020).
non-small cell lung carcinoma (3 papers, 2020 to 2024). A group of at least three distinct histological types of lung cancer, including non-small cell squamous cell carcinoma, adenocarcinoma, and large cell carcinoma. "In contrast, genes related to low C1QTNF6 expression were enriched in the mTOR signaling pathway, non-small-cell lung cancer, Notch signaling pathway, TGF-β signaling pathway, and ubiquitin-mediated proteolysis." (PMID 33123583, 2020). "What’s more, inhibition of C1QTNF6 could attenuated cell migration, invasion and promoted apoptosis in non-small cell lung cancer." (PMID 38711158, 2024).
autoimmune disorders (2 papers, 2013 to 2025). "By regulating complement activation, C1QTNF6 could prevent excessive tissue damage and autoimmunity, potentially limiting the progression of β-cell destruction in T1D patients." (PMID 40270961, 2025).
Cerebral ischemia (2 papers, 2021 to 2022). Restriction of arterial blood supply to the brain associated with insufficient oxygenation to support the metabolic requirements of the tissue. "Our findings demonstrate the inflammation‐modulatory effect of the H19/miR‐29b/C1QTNF6 axis in the mechanism of cerebral ischemia injury." (PMID 35322553, 2022).
hypothyroidism (2 papers, 2023 to 2024). Abnormally low levels of thyroid hormone. "The C1QTNF6 gene is known to carry two coding mutations, rs229527 (22:37,185,445:C,A) and rs229526 (22:37,185,382:G,C), that are associated with hypothyroidism-related phenotypes." (PMID 38919955, 2024).
adenomyosis (1 paper, 2022). The growth of endometrial tissue inside the muscular wall of the uterine corpus. "Similarly, the PGR-repressed genes Gadd45a, Ets2, Vstm4 and C1qtnf6 may be important genes related to progesterone resistance-mediated mechanisms of adenomyosis development." (PMID 35563206, 2022).
encephalitis (1 paper, 2025). An acute inflammatory process affecting the brain parenchyma. "Collectively, these results delineate a novel pathogenic axis, oar-miR-29b/C1QTNF6, which exacerbates neuro-inflammation and BBB disruption, contributing to the pathogenesis of E. faecalis-induced encephalitis." (PMID 41595449, 2025). "This study aimed to determine whether oar-miR-29b exacerbates E. faecalis-induced lamb encephalitis by targeting C1QTNF6 and disrupting blood–brain barrier integrity." (PMID 41595449, 2025).